IL6 (interleukin 6)
Diseases named in the same sentence as IL6 in open-access papers (continued):
Sharing a sentence is not in itself a finding about the gene and the disease.
tumor (continued). "Furthermore, administration of VSL#3 cocktail in AOM/DSS-treated mice significantly reduced the tumour load of animals, and decreased TNF-a and IL-6 in colonic tissue." (PMID 32575876, 2020). "Recently, it has been reported that hypofractionated irradiation with high dose per fraction reduced the level of circulating MDSCs in two HCC tumor-bearing mouse models and decreased the expression of MDSC-related stimulatory cytokines: IL-6, G-CSF and RANTES." (PMID 32849585, 2020). "The secretion of Il-6 and Il-8 by GC-derived mesenchymal stromal cells and further activation of the JAK2/STAT3 pathway induces the polarization of macrophages into pro-tumor M2 phenotype, which consequently promotes GC metastasis via advancing the EMT process." (PMID 32268527, 2020). "Moreover, TNF-α, IL-6, and several typical differentially expressed phosphorylated proteins (such as p-CCNB1, p-FOXO3, and p-STAT3) in tumor tissues, tumor cell viability, and cell cycle arrest assay in vitro further verify the results of IPA." (PMID 33344655, 2020). "We detected cytokines such IL-6, TNF-α, and TGF-β in mouse serum, and showed that the developed nanospheres induced an immune response, which may have regulated tumor killing." (PMID 32636744, 2020). "However, IL‐6 is also an important mediator of a dynamic tumour cell–CAF crosstalk by not only promoting fibroblast activation, but also supporting tumour cell growth in humans." (PMID 32133790, 2020). "This calculation revealed supra-additive upregulation of many of the same cytokines/chemokines in LKB1-reconstituted tumor spheroids co-cultured with MVNs, including CCL2 and CXCL10, while there were some differences such as IL-6, which was amplified, and CCL5, which was suppressed." (PMID 33013881, 2020). "Interestingly, while LIF is known to activate the same downstream signaling pathways as OSM and IL-6, STAT3 appears to play a contradictory role in the context of tumor cell dormancy in the bone." (PMID 32023849, 2020). "In line with this notion, blockade of the ActRIIB receptor to inhibit Mstn signaling prevented cachexia in C26 tumor bearing mice, without affecting increased circulating levels of IL-6, TNF-α, and IL-1β." (PMID 33329046, 2020). "The release of TGF-β, IL-6, and bFGF primes the surrounding stromal cells in order to support tumorigenesis by ensuring the ECM is dynamic and allows for the invasion and migration of the tumor." (PMID 33076397, 2020). "In addition to CORO1A, THBS1, PTP4A1, IL6, and CXCL16, the other nine genes were also upregulated in tumor tissues in TCGA." (PMID 32883954, 2020). "Furthermore, immunohistochemistry showed that iNOS, IL-6, MIP-3α and VEGF expression was positively correlated with TLR4 levels in transplanted tumor tissue in a TLR4-dependent manner." (PMID 32095158, 2020). "Once macrophages are recruited in the tumors, hypoxia-dependent transcription factors HIF1/2α reprograms macrophages into pro-tumoral phenotype that expresses IL-6, VEGF, and inducible nitric oxide synthase (iNOS) and arginase to promote tumor growth, angiogenesis, and immunosuppression." (PMID 32983125, 2020). "The production of pro-tumorigenic cytokines including IL-6, which induces STAT3 activation in hepatocytes, eventually promotes compensatory proliferation in hepatocytes that have escaped cell death, and subsequently, tumor development." (PMID 32363190, 2020). "Moreover, Wnt, IL-6, MAPK, SNARE, JNK, and HIF-1 pathways were upregulated in tumor-infiltrating I-MDSCs, suggesting their potential involvement in cell differentiation and tumor progression." (PMID 31941522, 2020). "TGF-β, IL-6, MMP-9 and VEGF in spleen tumours significantly decreased in XYS group." (PMID 33152259, 2020). "Notably, tumor cell-intrinsic STAT3 drives the expression of pro-tumorigenic cytokines (e.g., IL-6) and growth factors (e.g., VEGF), thus enhancing the recruitment of tumor-promoting myeloid cells such as TAMs or MDSCs to the TME." (PMID 32365499, 2020).
tumor (continued). "Furthermore, the correlation of acupuncture and moxibustion with T-bet/IFN-γ, GATA3/IL4, inflammation markers IL-6 and C-reactive protein (CRP), and tumor marker Ca199 was evaluated." (PMID 33144870, 2020). "CAR macrophages could contribute to shifting the TME towards tumor rejection by releasing inflammatory cytokines such as TNF, IL-6, IFNγ, and IL-12, by promoting T cell recruitment and function, and tumor growth suppression." (PMID 32429316, 2020). "On the one hand, OMVs transfer genetic material to tumor cells and, on the other, the OMV engagement of TLR2/TLR4 on epithelial cells triggers the release of exosomes, which, in turn, induces macrophages to produce pro-tumor cytokines (e.g., IL-6 and IL-18)." (PMID 32962159, 2020). "However, IL-6 together with PGE2 can promote tolerogenic phenotype on antigen-presenting cells, therefore, facilitating tumor growth." (PMID 33330068, 2020). "In contrast, IL-6 stimulates angiogenesis via two pathways—the NOTCH ligand Jagged pathway and the angiopoietin–tie pathway—which are considered to be the main pathways involved during pathological vascular remodeling and tumor angiogenesis." (PMID 33036128, 2020). "IFN-γ and IL-6 are proinflammatory cytokines and their elevated concentration in ICI responders could reflect spontaneous anti-tumor immune response, however, the explanation for higher IL-10 levels is much more obscure." (PMID 32992737, 2020). "In intestinal tumors, overactivation of NFκB signaling in CAFs inhibits tumor growth and angiogenesis in vivo, and the depletion of this CAF sub-population induces the increased production of HGF, IL-6 and FGF and increased the recruitment and activity of Treg cells." (PMID 33114328, 2020). "Furthermore, HTiO2 nanoparticle-based SDT upregulated the levels of pro-inflammatory cytokines such as interleukin (IL)-1β, IL-6, and tumor necrosis factor (TNF)-α within the tumor, increasing the immune response against the tumor." (PMID 33505987, 2020). "Testing combinations of various cytokines in T cell culture media revealed that tumor antigen specific CD4+ T cell growth was improved by culturing in IL-1β, IL-2, IL-6, IL-7, IL-15, IL-21, IL-23, and TGFβ, and that the addition of TGFβ was critical for the improved performance of the cocktail." (PMID 33362774, 2020). "Calcipotriol was shown to induce lipid droplet formation in PDAC PSCs, reduce tumor volume and stromal density, improve tumor vascularity, increase intra-tumoral gemcitabine (by 500%), block TGF-β/SMAD signaling and decrease the release of IL-6, CTGF and CXCL12." (PMID 32532126, 2020). "One showed that the trained animals did not undergo any changes in tumor mass compared to their matched control; however, muscle mass was preserved and inflammatory markers such as TNFα and IL-6 were reduced in the plasma of animals submitted to RT." (PMID 33613297, 2020). "Moreover, IL-6 recruits mesenchymal stem cells and immune cells in the TME, favoring the maintenance of an inflammatory milieu that promotes tumor growth." (PMID 33321934, 2020). "Gene expression of the tumor-promoting cytokines and mediators, such as transforming growth factor (TGF)-β1, vascular endothelial growth factor (VEGF), interleukin (IL)-8, and IL-6 were significantly suppressed by statins and zoledronic acid by up to 90% (p < 0.001)." (PMID 32727400, 2020). "Similarly, the suppression of IL-6 signaling axis in hormone-resistant TRAMP-C1 cells was shown to decrease EMT transition and tumor aggressiveness." (PMID 32585812, 2020). "Furthermore, the cytokines related to tumor growth, EMT, metastasis and drug resistance, such as IL-1B, IL-2, Il-4, IL-6, IL-10, IL-17, KC (GRO), were mainly expressed in mT obese models." (PMID 32411709, 2020). "Interestingly, IL-6, CXCL12, RANKL, CCL2, and TGFβ secreted by both tumor and bone stromal cells are well-studied cytokines that have been implicated in induction of this process." (PMID 32585812, 2020).
tumor (continued). "Finally, IHC analysis of tumor tissues in 120 patients showed that the TAM and the expression levels of IL-6 and TNF-α in tumor cells of FOBT-positive patients were significantly higher than those in FOBT-negative patients." (PMID 33643891, 2020). "In H22 tumor-bearing mice, oral administration of CSP resulted in increased body weights; peripheral white blood cell counts; thymus and spleen indices; and serum IL-2, IL-6, and TNF-α levels in vivo." (PMID 32595757, 2020). "However, the proportion of cytokine in tumour to sera varied from one cytokine to another; MIP-1α was only an average of 1.12-fold higher in the TME, while IL-6 was 10.29-fold higher." (PMID 32451467, 2020). "To evaluate the level change of cytokine in tumor microenvironment after TGF-β blocking, we examined the metastasis chemoattractants secreted by primed neutrophils in the microenvironment, including MMP-9, IL-6, ICAM-1, and NE." (PMID 32201528, 2020). "In vitro and in vivo experiments showed that UICC could facilitate the expression of IL-6 by combining with its promoter and directly interact with the phospho-STAT3 to improve its protein stability, thus promoting tumor growth and metastasis." (PMID 33520725, 2020). "Furthermore, CAFs support tumor invasion and dissemination by releasing MMPs (e.g., MMP-2 and MMP-9) and help cancer cell proliferation by releasing exosomes, SDF-1, FGF, IL-6, TGF-β, and osteopontin." (PMID 32499786, 2020). "Surprisingly, we found that although host IL‐6 levels increased in sera of cachectic tumour‐bearing mice, the levels were not significantly affected by interference with activin A signalling." (PMID 31436048, 2020). "As an inflammatory cytokine, IL-6 is mainly derived from stromal cells such as macrophages and fibroblasts around the tumor, and it is not secreted or is rarely secreted by the tumor cells themselves." (PMID 32149121, 2020). "There were fewer CD8+ tumor-infiltrating lymphocytes in untreated tumors, suggesting that CAFs regulate immunosuppressive tumor-infiltrating lymphocyte populations in the TME via IL-6." (PMID 32587587, 2020). "Although IL-1β, IL-6, and TNF-α have been shown to be regulated by MK2 signaling, cytokines often act in autocrine or paracrine manners to regulate production of other cytokines in the tumor microenvironment." (PMID 32216812, 2020). "Collectively, our study firstly demonstrate that GCAFs can upregulate NOX4 expression to promote VM formation and tumor growth in GBC, which may be achieved by paracrine IL-6-mediated IL-6-JAK-STAT3 signal pathway." (PMID 33153467, 2020). "Indeed, we also found that IL-6 and IL-8 expression was increased in CRC patients, as shown in the clinical database, and in OA-treated tumor cells." (PMID 32641980, 2020). "Tumor cells mobilize MDSC differentiation, proliferation, and migration toward tumor tissue by secreting vascular endothelial growth factor (VEGF), granulocyte-macrophage colony stimulating factor (GM-CSF), IL-6, IL-10, transforming growth factor-β (TGF-β) and other factors." (PMID 30792719, 2019). "Traditional tumor markers will be examined, including carcinoembryonic antigen (CEA), carbohydrate antigen 125 (CA-125), carbohydrate antigen 199 (CA-199), cytokeratin 19 fragment (CYFRA21-1), neuron-specific enolase (NSE), and interleukin 6 (IL-6)." (PMID 31195991, 2019). "In a previous study of patients with HCC, serum IL-6 level was significantly associated with advanced tumor characteristics, including large tumor size, presence of PVT, and extrahepatic metastasis, and IL-6 has also been proven as a significant predictor for unfavorable outcome." (PMID 30824840, 2019). "Finally, cytokines typically present within the tumor microenvironment, such as TNF, IL-1, and IL-6, have been shown to increase ST6Gal-I expression." (PMID 31610800, 2019).
tumor (continued). "Preclinical studies identified a CAF subpopulation expressing high amounts of α-SMA close to tumor cells and CAF subpopulations expressing low α-SMA and secreting IL-6 which could be responsible for the aggressiveness of PDAC." (PMID 31885581, 2019). "The tumor volumes were significantly larger in the MSC and IL-6 groups than in the Control group." (PMID 30755239, 2019). "Finally, we show both in tumor tissue and in cell lines that Stat3 supports SHH signaling which is potentiated by co-treatment with the STAT3 activating cytokine IL-6." (PMID 31683879, 2019). "Furthermore, IL-15, a pro-cytotoxic cytokine, was reduced, whereas IL-6, an inhibitor of the STAT-5 pathway and of the NK cell function, was increased in the tumor." (PMID 31105699, 2019). "Taken together, these results suggest that targeting IL-6 in the TME reduced tumor growth rate and IgM secretion while having no toxic effects on mice." (PMID 31164961, 2019). "Increased expression of IL-6 was found both in patients with CRC and in tumor tissue." (PMID 31795177, 2019). "Moreover, as compared with HCC group, CD56 expression was significantly reduced, while TNF-α and IL-6 expression was increased in the HCC-hMSCs group, which is suspected to contribute to tumor growth and metastasis." (PMID 31142737, 2019). "Furthermore, IL-6 can promote tumor angiogenesis by promoting the expression of VEGF and bFGF, and can also affect the growth of tumor cells by attracting more aggressive cells to the site of the tumor." (PMID 30651572, 2019). "STAT3 is a transcription factor for S1PR1 and, simultaneously, enhanced S1PR1 expression activates STAT3 and upregulates IL-6 expression, a proinflammatory cytokine crucial for STAT3 activation and inflammatory cell-mediated transformation and tumor progression." (PMID 31534132, 2019). "Firstly, in the tumor microenvironment, epithelial cells are not the main source of cytokines, particularly IL‐6, which is produced in large quantities by immune inflammatory cells." (PMID 31246342, 2019). "A reduction in pro-inflammatory cytokines, such as IL-6, TNF-α, and IFN-ɣ, was observed in mice treated with the triple combination, which suggests that a synergistic combination has significant effects against tumor progression." (PMID 31635311, 2019). "Th2 cells were shown to promote tumor development, unlike Th1 cells specific for the same antigens, suggesting that GM-CSF/IL-6/PGE2 M-MDSC cells induced in our model display the functional resemblance to M-MDSC in vivo." (PMID 30936876, 2019). "These MØs express CD163 and M2-specific markers (increased expression of FOLR2 and MAF and reduced expression of ActA), and show an upregulated expression of different factors that favour tumour progression (including, among others, IL-10, TGF-β, IL-6, IL-8, IDO1, COX2 and GAL-1)." (PMID 31337120, 2019). "In addition, in colorectal cancer, TAMs-derived IL-6 activates the STAT3 pathway, and activated STAT3 transcriptionally blocks the tumor suppressor miR-204-5p expression." (PMID 31629410, 2019). "SI-CLP was shown to induce the secretion of IL-1β, IL-6, IL-12, and IL-13 in PMA-treated THP-1 cells, suggesting that it may serve as a regulator of inflammation and in the tumor microenvironment." (PMID 32038607, 2019). "Hence, this combination can not only achieve a cancer-specific sensitisation to TRAIL-induced apoptosis, but also concurrently reduces the levels of potentially tumour-progressive cytokines such as CXCL5/ENA-78 and IL-6." (PMID 31010082, 2019). "There is a lack of information about the effect of IL-6 produced by TNBC tumor cells on the microenvironment entities, such as MSCs." (PMID 31014367, 2019). "It is known that pro-inflammatory cytokines such as IL-1β, IL-6, IL-8, IL-12, IL-18, and IFN-γ have been shown to enhance T-cell response, while anti-inflammatory ones, e.g., TGF-β and IL-10, promote T-cell exhaustion and infiltration in tumours." (PMID 31671581, 2019).
tumor (continued). "Moreover, combined inhibition of IL6 and IL8 significantly reduced tumor growth, promoted apoptosis, and enhanced TNBC sensitivity to paclitaxel." (PMID 31443516, 2019). "Taken together, these results raised the possibility that apigenin may inhibit tumor angiogenesis and VEGF expression through IL-6." (PMID 31572184, 2019). "This was further supported by the strong correlation between circulating concentrations of IL-6 and IL-8, and tumor burden, independent of survival." (PMID 31781510, 2019). "In addition, we transduced the tumor cells with reporter constructs for the expression of CDKN1A (coding for p21) and IL6, both considered markers of senescence." (PMID 31636264, 2019). "Peculiarly, IL-6 can be activated by an extracellular soluble form of IL-6 receptor (IL-6R), without a receptor of tumour cells." (PMID 31334678, 2019). "Acid-induced NF-κB activation downstream promotes the secretion of several cytokines, chemokines, and growth factors (IL1a, IL1b, IL6, IL8, IL23a, CCL5, CCL7, CXCL2, GM-CSF, and G-CSF) that can elicit local cancer aggressiveness, tumor immune escape, and tumor-induced nociception and hyperalgesia." (PMID 30825056, 2019). "This study reported a significant reduction in the IL-6 serum level in RT responders compared to non-responders, but the cohort of BC patients was heterogeneous for tumor stages and treatment types, including also combined CHT-RT (CRT)." (PMID 30658426, 2019). "Similarly, interleukin 6 (IL6) is also produced predominantly by CAFs and induces expression of resistance-mediating CXCR7 in tumor cells." (PMID 32118030, 2019). "This combination influences the IL-6-STAT-3 axis, tumour vascularisation and resistance to hypoxia." (PMID 30925774, 2019). "The influence of CAFs is effected through a paracrine function by means of the secretion of growth factors and cytokines, such as IL-1β, IL-6, IL-8, SDF-1, and NFκB, in order to induce immune cell recruitment that may contribute to tumor progression." (PMID 31086100, 2019). "Administration of antibiotics and probiotics or blocking the expression of toll-like receptor-4 (the LPS receptor) not only inhibits tumour cells proliferation but also reduces the infiltration of macrophages and the expression of tumour necrosis factor (TNF)-alpha and IL-6 in the liver tissue." (PMID 31671581, 2019). "It is also known that IL-6 can activate the STAT3 pathway in the tumor microenvironment, induce a large number of inflammatory genes and further promote angiogenesis to alter the proliferation of tumor cells." (PMID 31417646, 2019). "This study also reported that endotrophin facilitate tumor cell proliferation and metastasis through TGF-β activation as well as promote inflammation in the tumor microenvironment by upregulating inflammatory markers such as interleukin-6 and TNF-a." (PMID 30841909, 2019). "Or the reduction could be a consequence of stimulation, as it was reported, for example, that mouse neutrophils stimulated with IL-6 and G-CSF loose TRAIL expression and their anti-tumor properties." (PMID 31574961, 2019). "Additional RNAscope assays for IL6, CCL2, and POSTN were used to establish whether ANRIL correlated with increased tumor promoting cytokines." (PMID 31572679, 2019). "In addition, the change in weight, pain and quality of life, as well as the type of tumor removal surgery, hormone therapy and the uMARS score, can have a contribution in the changes found in the concentrations of CRP and IL-6." (PMID 31414667, 2019).